AHR (aryl hydrocarbon receptor)
Diseases named in the same sentence as AHR in open-access papers (continued):
Sharing a sentence is not in itself a finding about the gene and the disease.
atherosclerosis (continued). "Taken together, these studies suggest that AhR could be a potential drug target to interfere with the development and progression of atherosclerosis." (PMID 29984241, 2018). "Inflammatory responses contribute to AhR-regulated atherosclerosis." (PMID 29984241, 2018). "For example, activation of the AHR by dioxin induces an oxidative stress response, which might contribute to atherosclerosis via the oxidation of LDL, an early event in the formation of atherosclerotic plaques." (PMID 22222676, 2012). "Cross talk between the AHR and sex-hormone receptors is a well-known occurrence, and it is also well known that estrogen and testosterone are important players in atherosclerosis." (PMID 22222676, 2012). "However, we did not assess the activation of the AhR pathway in this study and did not investigate the association between serum AhR levels and subsequent atherosclerosis." (PMID 40508196, 2025). "One can hypothesize that AhR activation would abrogate the adverse role of KYNA in atherosclerosis development in IDO-deficient mice because it is known, for example, that AhR promotes IL-10 expression in inflammatory macrophages via the nongenomic Src–STAT3 signaling pathway." (PMID 39000041, 2024). "Interestingly, a recent study has demonstrated that the predominant and the earliest conversion of VSMCs was to osteoblast/chondrocyte lineages, while Aryl hydrocarbon receptor pathway activation diminished atherosclerosis disease-related VSMC switch to chondrocyte-like cells." (PMID 35163719, 2022). "Therefore, it has been suggested that AHR antagonists may be a potential therapeutic option for the treatment and/or prevention of atherosclerosis." (PMID 30513921, 2018). "Thus, the AhR could play a role in vascular aging and diseases, since atherosclerosis is seen as an age-related pathology of the vessels." (PMID 26790370, 2016). "In foam cells, AhR signaling induces the expression of proinflammatory interleukins IL-1β, IL-8, and TNF, thereby promoting atherosclerosis development." (PMID 39000041, 2024). "In atherosclerosis, upregulation of IDO stimulates KYN production, mediating aromatic hydrocarbon receptor (AhR)-induced exacerbation of vascular inflammation and promotion of foam cell formation." (PMID 38883986, 2024). "Thus, AhR activation might be involved in the BaP-accelerated development of atherosclerosis." (PMID 35739584, 2022). "Similarly, chronic use of classical AhR agonists such as FICZ or TCDD can disturb immune homeostasis and provoke serious adverse effects (e.g., atherosclerosis, hepatic fibrosis)." (PMID 41530817, 2026). "In a study on the relation of AhR signaling with the risk and complications of diseases associated with atherosclerosis, results revealed a negative role of AhR in atherosclerosis." (PMID 39000041, 2024). "For instance, in the absence of exogenous ligands, AhR can mediate proinflammatory effects and promote atherosclerosis progression." (PMID 39000041, 2024). "In the past, exogenous contaminants like 2,3,7,8-tetrachlorodibenzo-p-dioxin (TCDD) and B(a)P were considered the only ligands of AHR, and TCDD-mediated sustained AHR activation often leads to toxic results such as cell cycle arrest, chloracne and increased atherosclerosis." (PMID 37179416, 2023). "It was proven that the activation of the aryl hydrocarbon receptor AhR and also the promotion of oxidative stress by KYN, 3-KYN, 3-HAA, and QA may be important players in the initiation and progression of atherosclerosis." (PMID 33456671, 2020). "Exposure to contaminants containing ligands of AhR (dioxins, TCDD, PAH, benzo(α)pyrene) are thought to promote the development and progression of atherosclerosis, indicating that AhR may play a role in the regulation of atherosclerosis." (PMID 29984241, 2018).
atherosclerosis (continued). "A recent study uncovered a significant reduction in the activity of the KYNA branch (this phenomenon has never been reported in the context of atherosclerosis) and revealed that an important mechanism in the regulation of vascular inflammation is KYNA-mediated signaling through AhR." (PMID 39000041, 2024).
Hypertension (51 papers, 2011 to 2025). The presence of chronic increased pressure in the systemic arterial system. "TCDD-induced hypertension is associated with AhR activation, and resveratrol supplementation during gestation and lactation can mitigate TCDD-induced AhR signaling and oxidative stress." (PMID 41154514, 2025). "Within a maternal CKD-induced hypertension model, the therapeutic efficacy of tryptophan in lowering BP is associated with its modulation of the AHR signaling pathway." (PMID 38731818, 2024). "It has been found that polymorphisms of genes related to the AhR signaling cascade are closely related to the pathogenesis of essential hypertension." (PMID 39000041, 2024). "AhR KO models showed that AhR suppression can cause hypotension, hypertension, or attenuate HFD-induced endothelial dysfunction." (PMID 37686342, 2023). "TCDD-induced hypertension is associated with activation of AHR signaling, induction of TH17-dependent renal inflammation, and alterations of gut microbiota compositions." (PMID 35409313, 2022). "Both IS and IAA are well-known uremic toxins derived from tryptophan, which can bind the aryl hydrocarbon receptor (AHR) whose activation is related to an increased risk of hypertension." (PMID 35326133, 2022). "CYP1B1, transcriptionally inducible by AhR activation, is expressed in cardiovascular tissues and contributes to the development of hypertension and neointimal growth caused by vascular injury." (PMID 35739584, 2022). "Our assumption that this ligand-activated transcription factor plays a key role in clozapine-triggered adverse effects is supported by the fact that AhR signaling causes weight gain, hyperglycemia, and hypertension too." (PMID 34979820, 2022). "Of note is that resveratrol therapy prevented TCDD- or BPA-induced hypertension of developmental origins was linked to mediation of AhR signaling pathway." (PMID 33921641, 2021). "In a maternal CKD-induced hypertension model, maternal tryptophan therapy preventing offspring hypertension was associated with mediation of the AhR signaling pathway." (PMID 34371800, 2021). "Our previous study demonstrated that perinatal TCDD exposure exacerbated high-fructose diet-induced hypertension in male adult offspring, which was associated with the activation of AHR signaling pathway." (PMID 34573025, 2021). "In a maternal CKD-induced hypertension model, the BP-lowering effect of tryptophan therapy is associated with mediation of the AhR signaling pathway." (PMID 33218054, 2020). "Genetic polymorphisms of the AhR signaling pathway are reported to be closely associated with the pathogenesis of essential hypertension." (PMID 29984241, 2018). "The genetic environment and gene–gene interactions in the AhR signaling pathway are reported to determine susceptibility to essential hypertension." (PMID 29984241, 2018). "Activation of AhR has been associated with increased incidence of hypertension." (PMID 34979820, 2022). "Another of RBE’s protective mechanisms against CKD-induced hypertension may be associated with the mediation of the AhR signaling pathway." (PMID 35052587, 2021). "The AHR is involved in the transcription of distinct genes that are associated with hypertension." (PMID 31489946, 2019). "AHR is known to be associated with many different disorders, including hypertension." (PMID 30127255, 2018). "AhR−/− mice tend to develop hypertension at a modest altitude (1632 m), caused by hypoxia." (PMID 29984241, 2018). "Considering that tryptophan-derived uremic toxin are ligands for AHR and that AHR activation is associated with hypertension programming, AHR antagonists might provide a potential reprogramming strategy to prevent tryptophan metabolites-induced adverse outcomes." (PMID 36984857, 2023). "Additionally, whether NO deficiency, oxidative stress, activation of the RAS, and AHR signaling in other organs and tissues contribute to programmed hypertension requires further clarification." (PMID 30127255, 2018).
Hypertension (continued). "Maternal exposure to TCDD, a dioxin, has been shown to induce hypertension in offspring through activation of the AhR/CYP1A1 axis and promotion of TH17-mediated renal inflammation." (PMID 41154514, 2025). "We have been studying the link between the aryl hydrocarbon receptor (AhR) activation and the hypertension (HTN) secondary to obstructive sleep apnea (OSA)." (PMID 40253307, 2025). "BPA is likewise an AhR agonist, with prenatal exposure leading to offspring hypertension accompanied by increased renal expression of AhR, AHRR, CYP1A1, and ARNT." (PMID 41154514, 2025). "In maternal CKD, tryptophan supplementation altered tryptophan-metabolizing microbes and modulated AhR signaling, contributing to protection against programmed hypertension." (PMID 41008956, 2025). "Gestational PFOS exposure results in offspring hypertension in both sexes by 16 weeks of age, though the mechanistic contribution of AhR remains to be fully defined." (PMID 41154514, 2025). "In BPA-exposed pregnancies, for example, resveratrol alleviated offspring hypertension by restoring NO bioavailability, reducing oxidative stress, and suppressing AhR signaling." (PMID 41154514, 2025). "In particular, hypertension induced by HF diet plus BPA was linked to decreased NO bioavailability, increased oxidative stress, and activation of the AHR signaling pathway." (PMID 39449418, 2024). "It has been demonstrated that 3-methylcholanthrene can induce hypertension mediated by inactivation of endothelial NO synthase (eNOS) in mice, whereas in AhR−/− mice, hypotension is observed." (PMID 39000041, 2024). "AhR is a major participant in the pathogenesis of such cardiovascular pathologies as myocarditis, hypertension, coronary heart disease, and pulmonary arterial hypertension." (PMID 39000041, 2024). "In contrast, resveratrol supplementation during gestation and lactation demonstrated anti-inflammatory effects on offspring hypertension by regulating AhR signaling." (PMID 39339768, 2024). "The accumulation of T cells and pro-inflammatory cytokines plays a crucial role in the pathogenesis of kidney disease and hypertension, often triggered by the aryl hydrocarbon receptor (AhR) signaling pathway." (PMID 39339768, 2024). "BaP, a polycyclic aromatic hydrocarbon, contributes to cardiovascular disease via AHR activation, and gestational exposure leads to offspring hypertension." (PMID 38731818, 2024). "Previous research has shown that TCDD-induced hypertension correlates with AHR activation and TH17-induced renal inflammation." (PMID 38731818, 2024). "In a rat model of maternal BPA exposure, adult offspring developed hypertension alongside increased protein levels of AHR and mRNA expression of AHRR, CYP1A1, and ARNT in the offspring kidneys." (PMID 38731818, 2024). "Maternal exposure to the AHR ligand TCDD induces hypertension in offspring, correlated with AHR/CYP1A1 induction and TH17-mediated renal inflammation." (PMID 38731818, 2024). "High blood pressure is observed in mice with a knockout of the Cyp1a1 gene or of the AhR gene; AhR is a regulator of CYP1A transcriptional activity." (PMID 39457686, 2024). "Using a rat model of maternal CKD-induced hypertension, we observed that maternal tryptophan therapy preventing offspring’s hypertension coincides with restoration of the AhR signaling pathway and several tryptophan-metabolizing microbes." (PMID 35453625, 2022). "AHR expression was also higher in patients with hypertension (1.7 ± 0.2 vs. 1.0 ± 0.1; p = 0.010), with increased levels compared to those prior to treatment initiation." (PMID 35165326, 2022). "Another study demonstrated that adult rat progeny born to dams exposed to TCDD have hypertension, which is related to activation of AhR signaling, induction of TH17-dependent renal inflammation, and shifts of gut microbiota compositions." (PMID 35453625, 2022).
Hypertension (continued). "Activation of AhR and its downstream pathway have been reported to play a role in endothelium-dependent vascular dysfunction, hypertension, and cardiac hypertrophy inducing CYP1A1 expression and increasing ROS in the vasculature and heart." (PMID 35202128, 2022). "Conversely, antagonizing AHR signaling by resveratrol has been reported to protect adult offspring against hypertension programmed by environmental chemicals like TCDD and BPA." (PMID 34721300, 2021). "This study extends our knowledge of beneficial effects of resveratrol on hypertension programmed by perinatal TCDD exposure with particular emphasis on AHR signaling and gut microbiota." (PMID 34573025, 2021). "Our previous study showed resveratrol protected the programming of hypertension relevant to antagonizing the AHR signaling pathway in a maternal high-fat diet combined bisphenol A exposure model." (PMID 34573025, 2021). "Our study provides further evidence that supports the close link between CKD-induced hypertension and aberrant AhR activation, alterations in gut microbiota compositions, and reduced NO bioavailability." (PMID 35052587, 2021). "In a maternal BPA exposure model, adult offspring developed hypertension coinciding with increased AHR protein level as well as the mRNA expression of AHR target gene Ahrr, Cyp1a1, and Arnt." (PMID 34721300, 2021). "On the other hand, antagonizing AhR signaling by resveratrol has been reported to protect adult offspring against hypertension in several hypertension models of developmental origins." (PMID 34371800, 2021). "Hopefully, elucidation of the role of AHR in chemical-induced programmed kidney disease and hypertension will aid in the development of novel therapies." (PMID 34721300, 2021). "This is supported by the present observations, which demonstrated that CKD-induced hypertension coincides with the activation of the AhR signaling pathway as represented by increased ARNT and TIPARP expression." (PMID 35052587, 2021). "This review has provided an overview on reprogramming strategies against hypertension and kidney disease excepting tryptophan, which are related to the tryptophan metabolism, including melatonin and the AhR antagonist." (PMID 33218054, 2020). "This is the first study to describe how DMB protects against TCDD plus HFR-induced hypertension, and makes special emphasis on the AHR signaling, gut microbiota, the RAS, and the NO pathway." (PMID 32752013, 2020). "In conclusion, tryptophan supplementation in pregnancy offsets the effects of maternal CKD-induced programmed hypertension, primarily related to alterations of gut microbiota compositions and the AHR signaling pathway." (PMID 32604820, 2020). "The protective effect of tryptophan supplementation against maternal CKD-induced programmed hypertension is relevant to alterations to several tryptophan-metabolizing microbes and AHR signaling pathway." (PMID 32604820, 2020). "Resveratrol, a natural AhR antagonist, has been proposed to reprogram hypertension-related disorders." (PMID 33218054, 2020). "Several important mechanisms are involved in the protective actions of resveratrol against hypertension in adult offspring, including reducing oxidative stress, restoring NO bioavailability, and antagonizing the AHR signaling pathway." (PMID 31489946, 2019). "Our previous studies suggest that the NO and AHR signaling pathways both contribute to the pathogenesis of hypertension of developmental origins." (PMID 31489946, 2019). "Certain mechanisms contributing to the protective effects of resveratrol against HF + BPA-induced hypertension have been observed, such as the reduction of oxidative stress, the restoration of NO bioavailability, and the abrogation of AHR activation." (PMID 31489946, 2019).
Hypertension (continued). "This study casts a new light on the links of the ADMA–NO pathway, oxidative stress, and the AHR signaling pathway in the kidney by which maternal resveratrol treatment attenuates hypertension programmed by combined BPA and HF exposure in adult male offspring." (PMID 31489946, 2019). "The majority of single-nucleotide polymorphisms in the AhR pathway, such as rs2228099 (ARNT), rs1048943 (CYP1A1), rs762551 (CYP1A2), and rs1056836 (CYP1B1), are associated with susceptibility to hypertension." (PMID 29984241, 2018). "Further adjustment for a history of myocardial infarction, stroke, heart failure, diabetes, and medication for hypertension, diabetes or hyperlipidaemia only had a marginal effect on the correlations between AhR bioactivity and TEQ or individual POPs." (PMID 28839207, 2017). "Likewise, in maternal CKD models, offspring hypertension was mitigated by maternal tryptophan supplementation, implicating modulation of the AhR signaling pathway." (PMID 41008956, 2025). "In a rat model of cardiac hypertrophy, hypertension, and myocardial fibrosis induced by 5/6 nephrectomy, AhR pathway activation was observed, including AhR translocation and downstream protein Cytochrome P450 1(CYP1) expression, accompanied by increased ROS production detected via staining." (PMID 39931238, 2025). "Furthermore, resveratrol has been documented to function as an antagonist of the AHR, showing efficacy in mitigating offspring hypertension in alternative models of the developmental origins of hypertension." (PMID 38731818, 2024). "AHR KO mice developed hypotension at low altitudes and hypertension at modest altitudes, which might be related to elevated plasma endothelin-1 levels." (PMID 38731818, 2024). "Given that resveratrol has multiple biofunctions not just as an AHR antagonist, further research is needed to elucidate whether the use of a specific AHR antagonist can avert offspring hypertension attributed to tryptophan-derived uremic toxins in the future." (PMID 36984857, 2023). "As a natural AHR antagonist, resveratrol has been shown to prevent hypertension programming." (PMID 36984857, 2023). "It is known that activation of AHR is involved in the pathogenesis of hypertension." (PMID 36984857, 2023). "On one side, a possible concern for psychiatrists and their patients is whether AhR activation is involved in the side effects of clozapine treatment like agranulocytosis, hypertension, or weight gain." (PMID 34979820, 2022). "In addition, resveratrol was reported to act like an AhR antagonist, showing benefits in preventing offspring hypertension in other models of the early-life origins of hypertension." (PMID 35743061, 2022). "The current study was undertaken to interrogate whether perinatal TCDD exposure produces the programming of hypertension in adult life by mediating the AHR signaling pathway in adult offspring and whether maternal resveratrol supplementation was protected." (PMID 34573025, 2021). "CKD-induced hypertension is associated with an altered gut microbiota profile, dysregulated renal short chain fatty acid (SCFA) receptor expression, activation of the aryl hydrocarbon receptor (AhR) signaling pathway, and reduced nitric oxide bioavailability." (PMID 35052587, 2021). "Additionally, the TCDD-induced programming of hypertension is coincided with the activation of AHR signaling, TH17-induced renal inflammation, and alterations of gut microbiota compositions." (PMID 34573025, 2021). "In view of that activation of the AHR/CYP1A1 axis can induce vasoconstriction, whether DMB antagonizes AHR/CYP1A1 to protect offspring against TCDD-induced hypertension deserves further clarification." (PMID 34578924, 2021). "Prior research suggests the AHR signaling pathway is involved in TCDD-induced hypertension." (PMID 34573025, 2021). "Furthermore, resveratrol acting like an AHR antagonist benefits kidney disease and hypertension of developmental origins." (PMID 34721300, 2021).